PLK1 (polo like kinase 1)
Diseases named in the same sentence as PLK1 in open-access papers (continued):
Sharing a sentence is not in itself a finding about the gene and the disease.
prostate carcinoma (105 papers, 2011 to 2025). A carcinoma that arises from epithelial cells of the prostate gland. "High expression of PLK1 drives tumorigenesis, and its overexpression is directly associated with the onset of prostate cancer." (PMID 40809688, 2025). "PLK1 is overexpressed in prostate cancer and has been linked to higher tumor grades, implying that PLK1 plays a role in PCa tumorigenesis and progression." (PMID 38612439, 2024). "It was then found that PLK1 expression was increased in PTEN-deficient prostate cancer cells, which leads to the adaptation of cells to mitotic stress for survival." (PMID 37533462, 2023). "To further elucidate the oncogenic role of YTHDF1/PLK1 axis prostate cancer cells, we overexpressed PLK1 in YTHDF1-deficient PC-3 and DU145 cells." (PMID 36439881, 2022). "Our recent studies additionally demonstrated that when Gravin is lost in advanced stage prostate cancers, there is an increased incidence in PLK1‐associated errors, including mitotic delay and chromosome instability." (PMID 30414309, 2018). "Rather than directly inhibiting PLK1, we found that inhibition of PP2A causes selective lethality to PLK1-overexpressing breast, pancreatic, ovarian, glioblastoma, and prostate cancer cells." (PMID 27557495, 2016). "Polo-like kinase 1 (PLK1) is a key cell cycle regulator implicated in the development of various cancers, including prostate cancer." (PMID 27003818, 2016). "In other experiments, the levels of PLK1 in prostate cancer cells were deliberately lowered, which caused the cells to change to become more like epithelial cells and become less mobile." (PMID 27003818, 2016). "Targeted inhibition of PLK1 causes mitotic catastrophe and induction of apoptosis in prostate cancer cells." (PMID 24525428, 2014). "In the clinical setting, we have uncovered a HES6-associated signature that predicts poor outcome in prostate cancer, which can be pharmacologically targeted by inhibition of PLK1 with restoration of sensitivity to castration." (PMID 24737870, 2014). "This study discovered that inhibition of PLK1 could be a potential treatment option for prostate cancer patients with PTEN deficiency." (PMID 37533462, 2023). "The most notable observation is that the transition from primary prostate cancer to mPrCa is characterized by upregulation of processes associated with DNA replication, metastasis, and events regulated by the serine/threonine kinase PLK1." (PMID 34680307, 2021). "In addition, we observed that PLK1 inhibition is effective in suppressing the growth of taxane-resistant prostate cancer cells by causing mitotic aberration." (PMID 33207738, 2020). "PLK1 is frequently (>50%) overexpressed in prostate cancer (PCa), and PLK1 overexpression is linked to higher tumor grade, suggesting that PLK1 may play a pivotal role in PCa etiology." (PMID 27003818, 2016). "Our work delivers crucial molecular evidence for understanding EDs-driven cancer mechanisms and proposes targeting the EDs-PLK1 axis as a viable chemo-preventive and therapeutic strategy for prostate cancer." (PMID 41415207, 2025). "To confirm that PLK1 OE leads to the decrease of PHGDH in prostate cancer, we overexpressed PLK1 in LNCaP, C4–2 and 22Rv1 cells, and found that PLK1 OE leads to the decrease of PHGDH." (PMID 40475404, 2025). "These insights open new therapeutic avenues by targeting PLK1-regulated metabolic pathways in advanced prostate cancer." (PMID 40475404, 2025).
prostate carcinoma (continued). "The downregulation of PHGDH, a key enzyme often upregulated in other cancer types and non-catalytically expressed lower in cancer dissemination and metastasis, underscores PLK1’s unique ability to redirect metabolic flux in prostate cancer." (PMID 40475404, 2025). "The combination treatment of PHGDH inhibitor NCT-503 and PLK1 inhibitor Onvansertib effectively block the prostate cancer growth." (PMID 40475404, 2025). "To determine if knocking down (KD) PLK1 in advanced prostate cancer cells, such as DU145, leads to the upregulation of PHGDH, we knocked down PLK1 in both C4–2 and DU145 cells, and observed an increase in PHGDH." (PMID 40475404, 2025). "Metabolic profiling of PLK1-transformed prostate cancer cells revealed significant alterations in serine metabolism in advanced prostate cancers." (PMID 40475404, 2025). "PLK1 is overexpressed in various cancers, including prostate cancer, ovarian cancer, small cell lung cancer, and pancreatic cancer, and its expression level is often associated with poor prognosis." (PMID 40809688, 2025). "Our study reveals a novel regulatory axis in advanced prostate cancer, where PLK1 signaling reprograms serine metabolism, driving tumor growth and progression." (PMID 40475404, 2025). "The transition from primary prostate cancer to metastatic prostate cancer involves upregulation of DNA replication, mitosis, and PLK1 phosphorylation‐mediated events." (PMID 39949984, 2025). "In conclusion, our findings reveal how PLK1-driven metabolic reprogramming enhances the adaptability of prostate cancer cells, particularly by modulating serine metabolism, glycolysis, and sphingolipid synthesis." (PMID 40475404, 2025). "PLK1 is frequently overexpressed in a variety of malignancies, including prostate cancer, breast cancer, and colorectal cancer, where its high expression correlates with poor prognosis and enhanced tumor growth." (PMID 40475404, 2025). "We also found that ASCT2 is highly expressed in PLK1 highly expressed prostate cancer cell lines, like PC3 and DU145." (PMID 40475404, 2025). "PLK1 can activate the PI3K/AKT/mTOR pathway to elevate SREBP-dependent expression of key lipid biosynthesis enzymes in castration-resistant prostate cancer." (PMID 38649345, 2024). "USP7 deubiquitinated PLK1 to sustain its protein stability, and then promoted cell proliferation, taxane resistance, and chromosome misalignment in prostate cancer." (PMID 38625581, 2024). "We used these models to predict the activity of the molecules in the test set, and then we can use these models to predict the activity of new molecules as PLK1 inhibitors for prostate cancer treatment." (PMID 36676076, 2023). "PLK1 overexpression has been found in many types of different cancers (lung cancer, prostate cancer, colon cancer, etc.)and it plays an essential role in cell proliferation." (PMID 36676076, 2023). "In castration-resistant BRCA2-mutant prostate cancer cells (22RV1), olaparib was synergistic with the PLK1-inhibitor BI2536." (PMID 36765954, 2023). "PLK1 is overexpressed in various types of cancers, such as prostate cancer, non-small cell lung cancer, and head and neck cancer." (PMID 36805592, 2023). "Nuclear USP16 also deubiquitinates PLK1 for mitotic chromosome alignment and c-Myc in prostate cancer." (PMID 36980227, 2023). "The PLK1 inhibitor GSK461364 was also tested in combination with a BRD4 small inhibitor in castration-resistant prostate cancer both in vitro and in vivo, showing a strong synergistic effect." (PMID 35719948, 2022).
prostate carcinoma (continued). "According to that study, inhibition of PLK1 in metastatic prostate cancer cells triggered epithelial characteristics and suppressed cell migration." (PMID 35379935, 2022). "To sum up, we demonstrated that YTHDF1 promoted prostate cancer progression by increasing the translational efficiency of PLK1 in an m6A dependent manner." (PMID 36439881, 2022). "In this study we showed the upregulation of YTHDF1 in prostate cancer and its role in regulating prostate cancer tumorigenesis and metastasis through the induction of PLK1 mRNA translational efficiency in an m6A modification-dependent manner." (PMID 36439881, 2022). "Overexpression of PLK1 was observed in prostate cancer, colorectal cancer, neuroblastomas, and rectal cancer and was associated with poor prognosis." (PMID 35957699, 2022). "About 43% of PLK1 expression is knockdown by 50 nM of cationic BCD-siRNA conjugate using qRT-PCR to quantify in prostate cancer cells." (PMID 35631507, 2022). "PLK1 was over-expressed in many cancers, including prostate cancer, and scientists found that translation of the PP2A-PLK1 SDL interaction caused the expression of PLK1 and PP2A, which were commonly regarded as a biomarker in the cancer cells." (PMID 36376815, 2022). "Studies have shown that PLK1 is overexpressed in colorectal cancer, pancreatic cancer, gastric cancer, prostate cancer, thyroid cancer, bladder cancer, and other tumors, and the high expression of PLK1 indicates poor clinical prognosis." (PMID 35756492, 2022). "Consistent with previous studies, when YTHDF1 was knocked out in prostate cancer cells, the RNA level of PLK1 was relatively unchanged, whereas a prominent decrease in the protein level was observed." (PMID 36439881, 2022). "To further investigate the role of PLK1 in prostate cancer, we analyzed the expression of PLK1 in TCGA data." (PMID 36439881, 2022). "In another recent study, fostamatinib (which inhibits PLK1 as well as other serine-threonine kinases) was shown to be effective against the prostate cancer cell line (PC3)." (PMID 34680307, 2021). "In recent years, it has been found that PLK1 is highly expressed in cervical cancer, neuroblastoma cells, acute myeloid leukemia, prostate cancer and many other malignant tumors." (PMID 34696748, 2021). "In prostate cancer, olaparib (PARP inhibitor) treatment caused accumulation of cells in G2/M resulting in increased Plk1 expression and resistance." (PMID 33547392, 2021). "PLK1 has been identified as a potential target to enhance the therapeutic sensitivity of paclitaxel-resistant prostate cancer." (PMID 34178686, 2021). "PLK1 inhibition or depletion enhances the level of cytosolic and nuclear β-catenin in human prostate cancer cells." (PMID 34178686, 2021). "We therefore performed double immunofluorescence labeling of CD163, a marker of M2 macrophages, and PLK1 in a prostate cancer tissue microarray." (PMID 33197890, 2020). "This liposome showed a significant effect on cell uptake, increasing apoptosis in prostatic cancer cells via preserving the siRNA that reduced polo-like kinase 1 (PLK-1) expression by 22–75% (based on the type of synthesized liposome)." (PMID 32784981, 2020). "Studies have shown that PLK1 and CDC25C are overexpressed in prostate cancer, and PLK1 expression is also associated with high tumor grade." (PMID 32518522, 2020). "Xiang and coworkers used the prostate-specific antigen (PSA), which is overexpressed in prostate cancer, as trigger to specifically deliver siRNA against the polo-like kinase 1 (PLK-1) transcript." (PMID 34458758, 2020). "Double immunofluorescence labeling of a prostate cancer tissue microarray indicated that PLK1 expression correlated positively with numbers of infiltrating macrophages." (PMID 33197890, 2020).
prostate carcinoma (continued). "In this study, we constructed a model using a Cox proportional hazards model based on the expression of eight immune-related genes that were associated with prognosis in prostate cancer: EDNRB, ANGPTL2, TNFSF15, TNFRSF10D, EDN2, BMP2, NLRP14, and PLK1." (PMID 33197890, 2020). "What’s more, BI2536, an inhibitor of serine/threonine protein kinase Polo-like Kinase 1 (PLK1), has been reported to induce necroptosis in androgen-insensitive prostate cancer cells (LNCaP-AI) to overcome castration-resistance." (PMID 33665167, 2020). "Recent studies have demonstrated that Plk1 has a cell cycle–independent function in the regulation of EMT by activating CRAF/ERK signaling in prostate cancer or by activating AKT in gastric cancer." (PMID 31040125, 2019). "A PSMA aptamer-siRNA conjugate targeting prostate cancer was developed to suppress the expression of pro-survival genes such as polo-like kinase 1 (PLK1) and B cell lymphoma 2 (BCL2)." (PMID 29617327, 2018). "Similar findings in prostate cancer following Plk1 inhibition has suggested necroptosis as a mechanism of cellular death for some cells." (PMID 29402316, 2018). "The PLK1 scaffold Gravin is commonly misregulated in advanced prostate cancer and its depletion has been shown to increase PLK1 activity." (PMID 30414309, 2018). "The pro-mitotic protein PLK1 is upregulated in AR-independent prostate cancer cells, and PLK1 inhibitors promote necroptosis." (PMID 29371637, 2018). "Another study reported that small molecule (BI2536)-mediated inhibition of PLK-1 potentiates the anticancer activity of metformin (oxidative phosphorylation and mTORC1 inhibitor) in prostate cancer cells." (PMID 28415805, 2017). "Taken together, these results convincingly established a novel function of PLK1 as a critical regulator of EMT in prostate cancer." (PMID 28953239, 2017). "The role of PLK1 in EMT induction was further substantiated by the observation that PLK1 downregulation in metastatic prostate cancer cells enhances epithelial characteristics." (PMID 28953239, 2017). "In prostate cancer, siRNA-mediated depletion of PLK-1 increases the cytoplasmic and nucleo-plasmic level of β-catenin in an Axin2-dependent manner." (PMID 28415805, 2017). "PLK1 was differentially expressed and/or activated in prostate cancer cells (higher in metastatic prostate cancer cell lines and lower in non-metastatic cell lines)." (PMID 28953239, 2017). "This nanoformulation demonstrated significant cellular uptake of siRNAs and corresponding PLK1 gene knockdown in prostate cancer cells (DU145, VCaP and PC3)." (PMID 34322587, 2017). "These novel findings not only provide mechanistic insight into the important role of PLK1 overexpression in human cancer development and metastasis, but will also aid the advancement of the prevention and treatment of advanced prostate cancer human cancers." (PMID 28953239, 2017). "The RNA aptamer A10 is reported to deliver therapeutic CRISPR/Cas9-gRNA targeting polo-like kinase 1, a pro-survival gene overexpressed in most human tumors into prostate cancer cells via specifically binding to the cell-surface receptor PSMA." (PMID 28030843, 2017). "A protein called Polo-like kinase 1 (PLK1) plays a central role in the cell cycle and has been implicated in the development of various cancers, including prostate cancer." (PMID 27003818, 2016). "PLK1 is overexpressed in colorectal, breast, pancreatic, ovarian, glioblastoma and prostate cancer cells." (PMID 27557495, 2016). "Consistently, PLK1 downregulation in metastatic prostate cancer cells enhances epithelial characteristics and inhibits cell motility." (PMID 27003818, 2016).
prostate carcinoma (continued). "Since the expression of PLK1 is up regulated in the androgen insensitive LNCaP cells (LNCaP-AI), we first confirmed the expression of PLK1 in the prostate cancer cells and then examined the sensitivity to both cantharidin and nor-cantharidin." (PMID 27557495, 2016). "We quantitatively assessed PLK1 expression in a large novel human tissue microarray incorporating 61 men, some of whom had androgen naïve prostate cancer while others had hormone-relapsed disease." (PMID 24737870, 2014). "To further demonstrate the role of CDC25C, we used pharmacological inhibitors of PLK1 and CHEK1, in our LZTS1-deficient Docetaxel resistant prostate cancer cells." (PMID 24525428, 2014). "In prostate cancer cells, inhibition of PLK1 with BI2536 significantly potentiated Paclitaxel-mediated cell death while combination of BI2536 or BI6727 with histone deacetylases had antitumor effects in vitro." (PMID 24525428, 2014). "Our unbiased lipidomic screening found out the enhanced sphingolipid synthesis by PLK1 in prostate cancer cell line LNCaP, and we confirmed the significant incorporation of exogenous serine into ceramide, which accounts for over 1% of detected sphingolipids (Table EV4) in C4–2 PHGDH mutant cells." (PMID 40475404, 2025). "Through the integration of network toxicology, multi-omics analyses, a comprehensive assessment of 101 machine-learning algorithms, and subsequent in vitro validation, this research definitively establishes PLK1 as a key mediator of EDs-aggravated prostate cancer malignancy." (PMID 41415207, 2025). "Additionally, PELO promotes prostate cancer progression by enhancing PLK1-induced ubiquitination and degradation of Smad4." (PMID 40764425, 2025). "While evidence suggests that PLK1 plays a role in cancer metabolism, its specific impact on serine metabolism, particularly in advanced prostate cancer, remains unclear." (PMID 40475404, 2025). "Therefore, it is important to understand the factors that influence the efficacy of PLK1 inhibitors in prostate cancer." (PMID 40809688, 2025). "Additionally, the CETSA assay, a well‐established method for evaluating protein‐compound interactions, demonstrated that the L14‐8 treatment significantly increased the thermal stability of endogenous PLK1 in prostate cancer cell models." (PMID 40536697, 2025). "Small-molecule inhibitors of PLK1 can lead to the necroptosis of prostate cancer cells." (PMID 39858052, 2025). "Given the established critical role of PLK1 in the development and progression of prostate cancer and its widespread expression in multiple cell populations within the microenvironment, PLK1 was selected as the core target for subsequent mechanistic exploration." (PMID 41415207, 2025). "In prostate cancer cell lines (PC3 and LNCaP), the induction of apoptosis by apigenin was associated with increased p21 levels and a significant decrease in polo-like kinase 1 (PLK-1) expression." (PMID 38791608, 2024). "Moreover, YTHDF1 regulated prostate cancer growth and metastasis via increasing translational efficiency of polo-like kinase 1 (PLK1) in an m6A dependent manner, and the transcription of YTHDF1 was activated by the dysregulation of ELK1 in prostate cancer." (PMID 36439881, 2022). "Another study that tested PC3 prostate cancer cells showed that menthol has the potential to arrest the cell cycle at the G2/M phase by down-regulating the downstream signaling of polo-like kinase 1 (PLK1)." (PMID 35267408, 2022). "Research has demonstrated that PLK1 could affect androgen receptor elevation, lipid metabolism, and response to androgen signaling inhibitors in prostate cancer by regulating the PI3K/AKT signaling pathway." (PMID 36439881, 2022). "In addition, the protein level of PLK1 was downregulated in METTL3-KO prostate cancer cells and in cells treated with the m6A inhibitor DAA." (PMID 36439881, 2022). "PLK1 has been proven to be a potent and promising target for prostate cancer treatment." (PMID 35495629, 2022).